PCDHGB7 (protocadherin gamma subfamily B, 7)
Diseases named in the same sentence as PCDHGB7 in open-access papers (continued):
Sharing a sentence is not in itself a finding about the gene and the disease.
cancer (7 papers, 2019 to 2025). A tumor composed of atypical neoplastic, often pleomorphic cells that invade other tissues. "Unlike other members of the PCDHs family, the association between PCDHGB7 and cancer has not been fully understood." (PMID 39949775, 2025). "Clinical cancer samples (n=727) detection revealed that PCDHGB7 hypermethylation could be a diagnostic biomarker for cancer detection in a variety of cancers." (PMID 39949775, 2025). "Next, we further collected 46 para‐cancer (normal urothelial tissues adjacent to the UC) and 52 UC tissues from the clinic to analyze the DNA methylation status of PCDHGB7 by bisulfite‐PCR pyrosequencing." (PMID 40708980, 2025). "Previous studies based on TCGA and GEO databases (n=7114) have demonstrated that PCDHGB7 was hypermethylated in all cancer types." (PMID 39949775, 2025). "Previously, we revealed that PCDHGB7 served as a universal cancer‐only marker (UCOM) was hypermethylated in multiple cancer types." (PMID 40708980, 2025). "Our previous work identified that PCDHGB7 as a UCOM marker was significantly hypermethylated in multiple types of cancers." (PMID 40708980, 2025). "Of note, several studies have found that PCDHGB7 contributed to cancer development and functioned as a tumor suppressor gene." (PMID 39949775, 2025). "Hypermethylated PCDHGB7 has been identified as a new cancer marker and is applicable in early screening for EC and CC." (PMID 37368179, 2023). "Previously, our group found that PCDHGB7 was hypermethylated in various cancer types compared with their corresponding normal tissues, and hypermethylated PCDHGB7 was identified as a universal cancer only marker (UCOM)." (PMID 35059435, 2021). "In our previous study, PCDHGB7 was found to be hypermethylated in various types of cancer and identified as a universal cancer only marker (UCOM)." (PMID 35059435, 2021). "PCDHGB7 is a member of protocadherins, which plays an inhibitory role in tumorigenesis and cancer progression by inducing cell cycle arrest and apoptosis." (PMID 35059435, 2021). "It showed that PCDHGB7 was significantly hypermethylated in UC compared to the para‐cancer tissues." (PMID 40708980, 2025). "It turned out that PCDHGB7 was hypermethylated in urinary sediment of cancer cases." (PMID 40708980, 2025). "Hypermethylated PCDHGB7 was also found in CC, which can be applied for early cancer screening." (PMID 37368179, 2023). "In addition, HOXA11, HOXD13, and PCDHGB7 were confirmed as early methylated genes when human mammary epithelial cells (HMEC) converted into cancer cells in our previous study and in other studies." (PMID 31198475, 2019). "Importantly, we raised the concept of universal cancer only marker (UCOM) and identified hypermethylated PCDHGB7 as a UCOM." (PMID 35059435, 2021). "Specifically, the cancer universality of PCDHGB7 and TAGMe hypermethylation was demonstrated by the statistically significant differences generally found in malignant and nonmalignant samples from patients with different cancer types." (PMID 38587071, 2024). "However, the role and function of PCDHGB7 in cancers have not been fully elucidated." (PMID 39949775, 2025).
tumor (7 papers, 2020 to 2025). "A specific clinical reason for the predictive diagnostic function of PCDHGB7 methylation can be found in its association with ctDNA, mTBI, and tumor burden." (PMID 39949775, 2025). "Our ability to explore the predictive role of PCDHGB7 in immunotherapy was constrained by the availability of tumor tissue for PCDHGB7 detection." (PMID 39949775, 2025). "To investigate the relationship between aberrant PCDHGB7 expression patterns and methylation, we used the OncoDB databases to explore abnormal PCDHGB7 methylation patterns in normal and tumor tissues." (PMID 39949775, 2025). "The data revealed that the methylation levels of multiple sites in PCDHGB7 gene were higher in tumor tissues than in normal tissues, especially in the potential promoter region (141417677 to 141419677) in both LUAD and LUSC." (PMID 39949775, 2025). "According to our comprehensive analysis, PCDHGB7 expression was downregulated in LUAD and LUSC and associated with tumor prognosis." (PMID 39949775, 2025). "The methylation level of PCDHGB7 was upregulated in tumor tissue and negatively correlated with PCDHGB7 mRNA level." (PMID 39949775, 2025). "The DNAss score and EREG-METHss score demonstrated that PCDHGB7 expression was negatively correlated with tumor stemness LUAD (r = -0.2, p<0.001) and LUSC (r = -0.16, p=0.0027)." (PMID 39949775, 2025). "This constraint prevented us from elucidating potential contradictions in the predictive role of PCDHGB7 between tumor tissue and peripheral blood." (PMID 39949775, 2025). "Meanwhile, patients with high expression of PCDHGB7 in LUSC were more likely to develop FAT1 mutations, which would contribute to tumor development." (PMID 39949775, 2025). "We also found that PCDHGB7 upregulation was correlated with better HCC survival, which suggests a tumor suppressor role for PCDHGB7 in HCC." (PMID 36230503, 2022). "We further hypothesize that the methylation status of PCDHGB7 in ctDNA can reflect the overall epigenetic state of the tumor, and this state has a more accurate predictive value for the efficacy of immunotherapy." (PMID 39949775, 2025). "Interestingly, patients with liver metastasis or a high baseline tumor load were more likely to have high plasma PCDHGB7 methylation." (PMID 39949775, 2025). "PCDHGB7 demonstrated a positive correlation with inhibitory immune cells and a negative correlation with tumor mutational burden (TMB) and homologous recombination deficiency (HRD)." (PMID 39949775, 2025). "The data suggested that PCDHGB7 may play an important role in tumor initiation and development by affecting the immune response and DNA damage in tumor microenvironment." (PMID 39949775, 2025). "Moreover, the methylation level of PCDHGB7 was also significantly different in patients with tumor size less than 2 cm compared with BE groups (NEs and EHs)." (PMID 35059435, 2021). "The association between plasma PCDHGB7 methylation and gene mutations was equally notable, in that a statistically non-significant positive correlation (r = 0.28, p = 0.16) was identified between the tumor tissue TMB and plasma PCDHGB7 methylation." (PMID 39949775, 2025). "Collectively, these data suggested that high PCDHGB7 expression may promote a hybrid EMT state due to dysfunction of FAT1 protein, tumor stemness, and metastasis." (PMID 39949775, 2025). "However, it was encouraging that significant hypermethylated PCDHGB7 could be detected via Pap or Tao brush in early low-risk EC patients of stage IA without myometrial invasion, G1, tumor < 2 cm in greatest dimension and LVSI (-), which are suitable for a fertility preservation procedure." (PMID 35059435, 2021). "However, we did not observe different methylation levels of PCDHGB7 in EC among various tumor sizes, histologic subtypes, and stages with or without myometrial invasion and LVSI, which reports similar results in previous studies." (PMID 35059435, 2021).
tumor (continued). "In this study, we verify that hypermethylated PCDHGB7 can be used to early detect EC by Pap and Tao brush sampling even in EC patients of stage IA without myometrial invasion, G1, tumor < 2 cm in greatest dimension, lymphovascular space invasion (LVSI) (-) and without AUB/PMB." (PMID 35059435, 2021). "In addition to other members of the PCDH family, PCDHGB7 is closely related to proteins such as Protocadherin Fat 1(FAT1), mutL homolog 1(MLH1), and fragile histidine triad diadenosine triphosphatase (FHIT), which have been shown to be involved in DNA mismatch repair and related to tumor stemness." (PMID 39949775, 2025).
PCDHGB7 also shares sentences with these, for which no sentence is quoted: benign breast disease (2 papers); adenocarcinoma (1); bile duct cancer (1); hepatocellular carcinoma (1); leukemia (1); lung squamous cell carcinoma (1); renal pelvis cancer (1); Sotos syndrome (1); squamous intraepithelial lesions (1); ureter cancer (1).